EML6 (EMAP like 6)
Description:
Microtubule-associated protein that plays an important role in the regulation of oocyte meiotic progression by maintaining spindle integrity and facilitating proper chromosome alignment.
Synonyms: FLJ42562
Tractability: No criterion of Open Targets' tractability assessment is met for any kind of drug.
Gene: Protein-coding gene on chromosome 2 (54,723,499 to 54,972,025, forward strand). Ensembl gene ENSG00000214595.
Subcellular location: Cytoplasm; Cytoplasm, cytoskeleton, spindle
Subcellular location (Human Protein Atlas): Mitochondria; Vesicles
Gene Ontology:
Molecular function: microtubule binding
Cellular component: cytoplasm; spindle
Genetic constraint (gnomAD): Loss-of-function variants: 112 observed, 180.55 expected, observed/expected ratio (o/e) 0.62, 90% interval 0.53 to 0.73. The synonymous counts are far from expectation, so gnomAD's model fits this gene poorly and the ratio says little. Missense variants: 2,541 observed, 2,169.2 expected, observed/expected ratio (o/e) 1.17, 90% interval 1.13 to 1.21. Synonymous variants: 1,000 observed, 803.01 expected, observed/expected ratio (o/e) 1.25, 90% interval 1.18 to 1.31.
Homologues: Orthologues: macaque EML6 (99% identical), dog EML6 (98% identical), pig EML6 (98% identical), chimpanzee EML6 (98% identical), rabbit EML6 (98% identical), mouse Eml6 (97% identical), rat Eml6 (96% identical), tropical clawed frog eml6 (89% identical), zebrafish EML6 (72% identical), guinea pig EML6 (58% identical). Paralogues in human: EML5 (75% identical), EML4 (16% identical), EML1 (14% identical), EML3 (13% identical), EML2 (12% identical), CFAP44 (12% identical), WDR90 (11% identical), CFAP251 (8% identical), CFAP52 (6% identical).
Diseases named in the same sentence as EML6 in open-access papers:
EML6 is named in the same sentence as 11 diseases in open-access papers, as found by Europe PMC text mining. Sharing a sentence is not in itself a finding about the gene and the disease. The quoted sentences say what the papers report.
Astigmatism (2 papers, 2023 to 2025). A type of refraction error associated with abnormal curvatures on the anterior and/or posterior surface of the cornea. "The patient has a missense variant p.(Asp783Tyr) in heterozygosis in the EML6 gene, which is associated with astigmatism and keratoconus." (PMID 37895187, 2023).
Hypertension (1 paper, 2020). The presence of chronic increased pressure in the systemic arterial system. "In participants whose intake was less than 2 g/day, echinoderm microtubule-associated protein-like 6(EML6) rs67617923 was significantly associated with hypertension." (PMID 32854392, 2020). "While associations of several genetic variants in EML6 (e.g., rs17046380, rs72806698) with hypertension have been noted previously, rs67617923 is a novel genetic variant that was newly discovered in our study." (PMID 32854392, 2020). "In the participants with sodium intake <2 g/day, we found significant association of rs67617923 in EML6 with increased risk of hypertension." (PMID 32854392, 2020).
keratoconus (1 paper, 2023). A degenerative, structural disorder of the eye, characterized by a cone-shaped protrusion of the cornea. "In the genetic study of the proband, a missense variant in heterozygosis was found in the EML6 gene, directly related to keratoconus, as described in family OFT-00817." (PMID 37895187, 2023).
language disorder (1 paper, 2022). A category of disorders characterized by an impairment in the development of an individual's language capabilities, which is in contrast to his/her non-verbal intellect. "The genes PDE4D, FOXP2, and EML6 code for a cAMP phosphodiesterase, a transcription factor implicated in a speech and language disorder, and a microtubule associated protein, respectively." (PMID 36192459, 2022).
lung adenocarcinoma (1 paper, 2022). A carcinoma that arises from the lung and is characterized by the presence of malignant glandular epithelial cells. "The EML6-ALK fusion variant associates with crizotinib response in lung adenocarcinoma." (PMID 35832546, 2022).
schizophrenia (1 paper, 2022). A major psychotic disorder characterized by abnormalities in the perception or expression of reality. "The ependymal cluster exhibited the largest number of DEGs between schizophrenia and controls, including reduced PDE4D, and increased FOXP2 and EML6 expression activity in schizophrenia." (PMID 36192459, 2022). "Therefore, the altered expression of EML6 in the midbrain ependymal cells might reflect a general feature of schizophrenia ependymal cells, which could affect the beating of ependymal cilia and thus contribute to the reduced neurogenesis reported in the subependymal zone of schizophrenia patients." (PMID 36192459, 2022).
tumor (1 paper, 2021). "However, whether USP44, E2FS, and EML6 may play a role in regulating tumor-immune interaction remains to be determined." (PMID 34267181, 2021).
EML6 also shares sentences with these, for which no sentence is quoted: asthma (1 paper); cancer (1); neurodevelopmental disorder (1); rheumatoid arthritis (1).